ZFP30 (ZFP30 zinc finger protein)
Description:
May be involved in transcriptional regulation.
Synonyms: KIAA0961; ZNF745
Tractability: PROTAC: UniProt records ubiquitination sites on it; ubiquitination databases record sites on it.
Gene: Protein-coding gene on chromosome 19 (37,613,749 to 37,692,337, reverse strand). Ensembl gene ENSG00000120784.
Subcellular location: Nucleus
Subcellular location (Human Protein Atlas): Cytosol
Pathways (Reactome):
Gene expression (Transcription): Generic Transcription Pathway
Gene Ontology:
Molecular function: DNA-binding transcription factor activity, RNA polymerase II-specific; RNA polymerase II cis-regulatory region sequence-specific DNA binding
Biological process: regulation of transcription by RNA polymerase II; regulation of DNA-templated transcription
Cellular component: nucleus
Genetic constraint (gnomAD): Loss-of-function variants: 19 observed, 21.26 expected, observed/expected ratio (o/e) 0.89, 90% interval 0.62 to 1.31. The upper end of that interval is the gene's LOEUF score, 1.31, which puts it in group 5 of 6, group 1 being the genes least tolerant of losing a copy. Missense variants: 556 observed, 636.51 expected, observed/expected ratio (o/e) 0.87, 90% interval 0.81 to 0.94. Synonymous variants: 170 observed, 207.32 expected, observed/expected ratio (o/e) 0.82, 90% interval 0.72 to 0.93.
Homologues: Orthologues: chimpanzee ZFP30 (99% identical), macaque ZFP30 (98% identical), dog ZFP30 (92% identical), pig ZFP30 (92% identical), rabbit ZFP30 (85% identical), mouse Zfp30 (85% identical), rat Zfp84 (83% identical), guinea pig ZFP30 (81% identical). Paralogues in human: ZFP82 (77% identical), ZFP14 (71% identical), ZNF546 (59% identical), ZNF540 (58% identical), ZNF571 (56% identical), ZNF30 (54% identical), ZNF780B (54% identical), ZNF461 (53% identical), ZNF573 (52% identical), ZNF790 (51% identical), ZNF841 (51% identical), ZNF267 (50% identical), and 164 more.
Diseases named in the same sentence as ZFP30 in open-access papers:
ZFP30 is named in the same sentence as 7 diseases in open-access papers, as found by Europe PMC text mining. Sharing a sentence is not in itself a finding about the gene and the disease. The quoted sentences say what the papers report.
asthma (1 paper, 2018). "Using a mouse (Mus musculus) model of asthma applied to the Collaborative Cross population, we previously identified a lung gene expression quantitative trait locus (eQTL) for Zinc finger protein 30 (Zfp30) that was also a QTL for neutrophil recruitment and the hallmark neutrophil chemokine CXCL1." (PMID 29242385, 2018).
Hepatic steatosis (1 paper, 2025). Steatosis is a term used to denote lipid accumulation within hepatocytes. "ZFP30 is a member of the Krüppel-associated box zinc finger protein (KRAB-ZFP) family; recent studies have shown that chlorogenic acid inhibits the upregulation of ZFP30 in NAFLD and promotes the expression of PPARα, thereby enhancing FAs β-oxidation and alleviating hepatic steatosis." (PMID 41154556, 2025).
orchitis (1 paper, 2021). Inflammation of one or both testes due to viral or bacterial infections. "Uqcrb, Sod1, Zfp30, and Zzz3 negatively regulated collagen expression during orchitis." (PMID 35111154, 2021).
ZFP30 also shares sentences with these, for which no sentence is quoted: Cerebral visual impairment (1 paper); Intellectual disability (1); Streptococcus pneumoniae infection (1); tumor (1).